BCL2 (BCL2 apoptosis regulator)
Diseases named in the same sentence as BCL2 in open-access papers (continued):
Sharing a sentence is not in itself a finding about the gene and the disease.
glioma (continued). "In conclusion, we speculate that Wogonin might promote glioma cell apoptosis by upregulating Bad gene expression and cleaved caspase-3 gene activation and by downregulating Bcl-2 expression." (PMID 33897434, 2021). "In this experiment, we found that the LINC01087 expression in glioma tissues and cells increased obviously, and it could act as miR-384 sponge and participate in the development of glioma by regulating Bcl-2." (PMID 34459789, 2021). "Furthermore, miR-181b is also a potential therapeutic target for glioma chemoresistance because it regulates the sensitivity of gliomas to TMZ by targeting BCL-2 and EGFR." (PMID 34745938, 2021). "Furthermore, we found that inhibition of STAT3 enhanced the upregulation of Bax and downregulation of Bcl-2 in glioma cells treated with the combination of sorafenib and TMZ." (PMID 34277607, 2021). "Furthermore, through correlation analysis, we found that miR-384 was negatively correlated with LINC01087 and Bcl-2 expression in tumor tissues of glioma patients." (PMID 34459789, 2021). "Indeed, Bcl2 protein has been reported to be expressed at high levels in malignant gliomas mainly glioblastomas and recurrent gliomas and was found to enhance migration and invasion capability of human glioma cells." (PMID 32856872, 2020). "XIST crosstalk with miR-204-5p mediated glioma cell apoptosis via the Bcl-2 pathway." (PMID 32489472, 2020). "Similarly, studies in which high expression of the Bax antagonist Bcl-2 has been reported to correlate with better prognosis can be found for colorectal, breast, glioma, gastric and non small cell lung cancer." (PMID 32054850, 2020). "Moreover, miR34a has been reported to modulate glioma cells apoptosis by targeting BCL2 and stimulating senescence in glioma cells by inducing DNA damage." (PMID 33287106, 2020). "In addition, we observed significant downregulation of the antiapoptotic protein Bcl-2 and upregulation of the proapoptotic protein Bax in glioma cells treated with α-m-Dox/M." (PMID 33116114, 2020). "XIST crosstalk with miR-204-5p mediates glioma cell apoptosis via the Bcl-2 pathway." (PMID 32489472, 2020). "Moreover, we discovered that XIST crosstalk with miR-204-5p mediates glioma cell apoptosis via the Bcl-2 pathway." (PMID 32489472, 2020). "Moreover, CRNDE also acted as a ceRNA that bound to and negatively regulated miR-136-5p in glioma, subsequently protecting Bcl-2 and Wnt2 from miR-136-5p-mediated inhibition." (PMID 32435153, 2020). "According to a previous report by our group, mifepristone reduces Bcl-2 expression in glioma cells." (PMID 33123485, 2020). "In this study, we suggest that Bcl2 inhibition by ALO induces apoptosis in glioma cells." (PMID 31534865, 2019). "Moreover, western blot and qPCR analysis showed that ALO downregulated Bcl2 expression in human glioma cell lines, SK-N-AS and U118." (PMID 31534865, 2019). "Furthermore, caspase-3 has an active function in the cleavage of the Bcl-2 protein and other substrates such as Bcl-XL, which normally functions to prevent apoptosis in glioma cells." (PMID 31100944, 2019). "Combination of Bcl-2 inhibitors with radiotherapy/chemotherapy could overcome resistance of glioma cells to these treatment." (PMID 30446901, 2019). "Indeed, the addition of BH3 mimetics such as ABT-737 (which inhibits pro-survival BCL2 proteins) rescued the ability of H-1PV to induce apoptosis in these cells, thereby strongly potentiating H-1PV glioma cell oncolysis." (PMID 31216641, 2019). "Similarly, another non-coding RNA, linc-CCAT2 derived from glioma EVs promoted angiogenesis in vitro and in vivo in addition to enhancing Bcl-2 expression and inhibiting Bax and caspase-3 expression in endothelial cells, decreasing apoptosis." (PMID 32038644, 2019).
glioma (continued). "Furthermore, SRT2183 induced glioma cell cycle arrest and apoptosis, accompanying by upregulation of the pro-apoptotic Bim and downregulation of Bcl-2 and Bcl-xL." (PMID 31319814, 2019). "Furthermore, the expression of BCL2 was inversely correlated with the miR-153-3p levels in radioresistant glioma tumors (p = 0.0328)." (PMID 30537994, 2018). "This suggest that the efficacy of tinostamustine may be influenced by Bcl2 levels also if further studies should be necessary including Bcl2 transfection in low Bcl2 expressing glioma cell lines." (PMID 29486795, 2018). "Notably, BCL2 was predicted and confirmed as a direct target gene of miR-153-3p participating in the radiosensitivity in glioma." (PMID 30537994, 2018). "On the other hand, the use of inhibitors of the HSF-1/HSP90/BAG3 pathway increases the antineoplastic effect of AT101, reactivating caspase-dependent apoptosis in the U252 and U343 glioma cell lines through a downregulation of Bcl-2 and Mcl-1 and an increase of Bax and mitochondrial dysfunction." (PMID 30486451, 2018). "Furthermore, down-regulation of BCL2 was observed in radiosensitive miR-153-3p-overexpressing glioma xenograft mice model." (PMID 30537994, 2018). "As BCL2 was a downstream target of miR-153-3p, we speculated that miR-153-3p might enhance radiosensitivity of glioma cells through directly targeting BCL2." (PMID 30537994, 2018). "Nonetheless, we utilized longitudinal bioluminescence imaging to monitor any changes in the progression of U251.eGFP.ffluc glioma orthotopic xenografts if treated with either parental or Bcl-2-expressing CD-NSCs, followed by 5 consecutive days of prodrug administration." (PMID 30026762, 2018). "Fibroblast growth factor 4 (FGF4) also has been correlated with a greater malignancy profile in high-grade gliomas.The radioresistant cells had upregulated expression of many anti-apoptotic genes, including BCL2, CD74, and WT1, which regulates GBM cells proliferation and apoptosis." (PMID 30344926, 2018). "miR-181d acts as a glioma suppressor by targeting K-ras and Bcl-2." (PMID 29382357, 2018). "Here, our data show that transient overexpression of Bcl-2 by human CD-NSCs can increase their survival posttransplantation, which translates to improved therapeutic efficacy in an orthotopic xenotransplantation glioma model." (PMID 30026762, 2018). "As2O3 downregulated Bcl-2 and rendered C6 and 9 L glioma cells vulnerable to apoptotic cell death." (PMID 29610575, 2018). "Thus, rescue experiments were performed to investigate the effect of BCL2 on the miR-153-3p-mediated radiosensitivity in glioma cells." (PMID 30537994, 2018). "Next, we successfully acquired mTOR and Bcl‐2‐overexpressed glioma cells." (PMID 28064447, 2017). "Taken together, these results indicated that CHL1-dependent anti-apoptosis in glioma cells may be partially mediated by regulation of the death receptor signaling pathway composed of Bax, Bcl-2 and active caspase-3." (PMID 29089868, 2017). "In addition, our current finding showed that mTOR and Bcl‐2 were regulated by miR‐497 directly, highlighting the potential role of miR‐497 overexpression for glioma to develop a TMZ‐resistance phenotype." (PMID 28064447, 2017). "Subsequently, to investigate the aspirin associated apoptotic route via SHH/GLI1 inhibition at protein level, Western blot showed that Caspase-3, Bax and cleaved PARP increased in a dosedependent manner and that Bcl-2, an anti-apoptosis protein, decreased in the glioma cells treated by aspirin." (PMID 28446712, 2017). "To verify this, we performed mTOR and Bcl‐2 loss‐of function experiments in U87‐TR and SF295‐TR cells to investigate whether the silencing of mTOR and Bcl‐2 in glioma cells could regulate the chemotherapy resistance of glioma cells in vitro." (PMID 28064447, 2017).
glioma (continued). "The flow cytometry assay performed in the present study showed that anoikis resistance was suppressed in the HULC-silenced U87MG and U251 cell lines, suggesting that HULC was correlated with glioma anoikis resistance through the regulation of the Bcl-2/Bax ratio and caspase-3/8 activity." (PMID 26894862, 2016). "Moreover, miR-181c modulates the proliferation, migration, and invasion of neuroblastoma cells by targeting Smad7, while miR-181d acts as a tumor suppressor in glioma by targeting K-ras and Bcl-2." (PMID 26473853, 2015). "And Bcl-2 proteins were widely studied in glioma cells and the development of MG." (PMID 25658946, 2015). "Thus, to elucidate the effects of RF exposure on growth, apoptosis, and malignancy of human glioma cells, we analyzed c-myc, Emp-1, bcl-2, and bax expression by real-time PCR and Id-1 protein levels by western blotting." (PMID 26253141, 2015). "In a previous report, miR-136 was identified as a negative regulator of Bcl-2 in glioma cells." (PMID 26450567, 2015). "Interestingly, resistance to Temozolomide (TMZ), an anti-tumor pharmaceutical studied for treating gliomas, is influenced by Cx43 expression and correlates with mitochondrial alterations including release of CytC and increased Bcl-2/Bax ratios." (PMID 24847208, 2014). "The HIV protective effect on astrocytes may parallel cell death resistance in gliomas by a common mechanism involving CytC and Bcl-2." (PMID 24847208, 2014). "Also, inhibition of antiapoptotic Bcl-2 by a pan-Bcl-2 inhibitor (−)-gossypol leads to autophagic death in gliomas and enhances the action of TMZ." (PMID 23459853, 2013). "Finally, Bcl-2 has promigratory and proinvasive activities, as Bcl-2-expressing glioma cell lines exhibited enhanced expression and activity of the proprotein convertase furin, which proteolytically activates proinvasive metalloproteinases (MMP) and TGF-β." (PMID 22431925, 2012). "However, according to our results, the impact of the up-regulation of miR-15b on the expression of BCL2 seems to be less pronounced in gliomas." (PMID 21655185, 2011). "In this study, gene silencing of HOXD9 induced apoptosis and reduced the expression of BCL-2 in glioma cells, indicating that HOXD9 may support the cell survival." (PMID 21600039, 2011). "Similarly, we observed that stable expression of Bcl-2-targeted to the ER or WT Bcl-2 expressed not only in the ER but also in the mitochondria and nuclei, reduced cerulenin-mediated glioma cell death." (PMID 16969344, 2006). "Several clones of the rat glioma A15A5 cells stably transfected with human Bcl-2 or Bax were used." (PMID 15331018, 2004). "Several previous studies have also examined bcl-2 staining in gliomas." (PMID 12085183, 2002). "Additionally, DMAMCL may target the Bcl-2 signaling pathway, further enhancing its antitumor efficacy in glioma cells." (PMID 40051564, 2025). "As p38 MAPK-induced BAX/Bcl-2/caspase-3 apoptosis signaling is involved in glioma cell proliferation, p38 MAPK may play a pivotal role in controlling PGCs output by eliminating damaged or unscheduled pluripotency expression through mediation with Bcl-x and Bax proteins." (PMID 38911025, 2024). "Furthermore, in glioma cell lines and ovarian granulosa cells, TMCO1 knockdown is associated with decreased levels of BCL-2, potentially affecting the BH3 profile and therefore sensitivity to BCL-2 inhibitors used in our study." (PMID 39353922, 2024). "Furthermore, a previous study showed that the overexpression of miR-320b could suppress cell proliferation via the Bcl-2/Bax apoptosis pathway and serve as a novel prognostic marker for glioma." (PMID 36996494, 2023).
glioma (continued). "Therefore, the aim of this study was to assess, for the first time, the contribution of the formation of the Bcl-2 and beclin-1 complex in the context of the glioma cell elimination through programmed cell death induction using the combined action of LY294002 and sorafenib." (PMID 38067099, 2023). "Finally, Bcl-2 inhibitors were screened as candidates for adjunct immunotherapy of gliomas." (PMID 35990696, 2022). "In addition, miRNA-153-3p improves radiosensitivity in human glioma cells by targeting BCL2." (PMID 36038831, 2022). "Bcl-2 was also found to be downregulated in glioma cells treated with aplysin, implying that this antiapoptotic protein may be also involved in its effect on the action of temozolomide on glioma cells." (PMID 34440090, 2021). "In addition, miR-181a-5p suppresses proliferation and induces apoptosis of glomerular mesangial cells by suppressing KLF6 and BCL2 expression via reduction of WNT/β-catenin signaling in human diabetic nephropathy and of glioma cell lines through suppression of the gene encoding for Cyclin B1." (PMID 33572377, 2021). "It suggested that LINC01087 could suppress the growth of glioma by regulating miR-384/Bcl-2 axis." (PMID 34459789, 2021). "In vivo repaglinide prominently prolonged the median survival time of mice bearing orthotopic glioma, reducing Bcl-2, Beclin-1 and PD-L1 expression in glioma tissues and indicating that repaglinide may exert its anti-cancer effects via apoptotic, autophagic and immune checkpoint signaling." (PMID 33212778, 2020). "Additionally, over-expressed Bcl2 suppressed the pro-apoptosis effect of ALO in glioma." (PMID 31534865, 2019). "In addition, Bcl-2 overexpression could rescue ALO-induced Bcl-2 inhibition and suppress pro-apoptotic effects in glioma cells." (PMID 31534865, 2019). "Therefore, we hypothesized that aberrant expression of miR-153-3p might affect the radioresistance of glioma cells by regulating BCL2." (PMID 30537994, 2018). "Further, it was observed that apoptosis rate of glioma cells was increased after Prucalopride treatment, in support of this, the pro-apoptosis markers Cleaved caspase-3 and Bax were up-regulated while anti-apoptosis marker Bcl-2 was down-regulated by Prucalopride." (PMID 29866060, 2018). "Furthermore, BCL2 could be targeted by miR-16 and miR-181a involved in the tumorigenicity and radioresistance of glioma cells." (PMID 30537994, 2018). "Reports have shown that downregulation of miR-136-5p in human gliomas is significantly associated with a more aggressive and poor prognostic phenotype; conversely, its overexpression promotes apoptosis and modulates sensitivity to cisplatin by targeting AEG-1, Bcl-2, and E2F1." (PMID 29152149, 2017). "In addition, the knockdown of mTOR and Bcl‐2 reduced the tolerance of glioma cells to TMZ." (PMID 28064447, 2017). "Additionally, forced down-regulation of ZEB1-AS1 could dramatically promote apoptosis by increasing the expression level of Bax and reducing Bcl-2 expression in glioma." (PMID 27589728, 2016). "Furthermore, miR-92b could regulate the expression of downstream genes of the Wnt/beta-catenin signaling pathway, such as Bcl2, c-myc and p-c-Jun, in glioma cells." (PMID 24325785, 2013). "In addition, ABT-737- and HA-14-1-treated glioma-bearing mice showed reduced tumor formation and increased survival, suggesting that targeting Bcl-2/Bcl-xL/Bcl-w alone or in combination with chemotherapy and radiation regimens represents a promising therapeutic approach." (PMID 22431925, 2012). "Similarly, we also found that PK treatment causes a decreased Bcl-2 expression and increased level of Bax, which may be responsible for the induction of apoptosis in SHG-44 glioma cells." (PMID 20953401, 2011). "Thus, it is possible that miR-181b may modulate the chemoresistance of glioma stem cells by targeting Bcl-2." (PMID 23554660, 2010).
glioma (continued). "PCTC, a derivative of MA, elevated the levels of p-JNK and p-p38, which are associated with iROS generation, ultimately leading to cell apoptosis in glioma cells by augmenting caspase 3/7, PARP, and repressing the level of the anti-apoptotic protein Bcl-2." (PMID 39863145, 2025). "In gliomas, miR-136 inhibits proliferation and induces apoptosis by regulating AEG-1 and BCL-2 gene expression." (PMID 40104500, 2025). "Upregulation of anti-apoptotic Bcl-2/BCL-xL can suppress apoptosis and autophagy, shifting glioma cells toward survival mechanisms under cytotoxic stress." (PMID 41511337, 2025). "In MOLM13 cells, we observed Bcl-2 downregulation, which is consistent with PARP cleavage reported in HL-60 leukemia and U251 glioma." (PMID 40735485, 2025). "It is known that CASP3 activity and apoptosis in glioma cells are regulated by the balance between pro‐apoptotic BAX and anti‐apoptotic Bcl‐2 proteins." (PMID 40318008, 2025). "The pentapeptide increases caspase 3, 8, and 9 activities and Bax, Fas, and FasL expression, decreases Bcl-2 expression, augments cytoplasmic Ca++ influx, and increases NFAT1 levels in the nucleus of C6 glioma cells." (PMID 39063232, 2024). "IsocuB was found to inhibit glioma growth by suppressing PDK1, Bcl-2, PI3K-AKT, and MAPK signaling pathways, as well as the activation of MMP-2/9." (PMID 38835342, 2024). "Western blot and immunocytochemistry revealed decreased Bcl-2 levels across all cell lines, with the most significant reduction (45.9%) in RG-2 cells treated with the lower RSV/TMZ dose compared to normal glioma cells." (PMID 39769099, 2024). "Our findings demonstrate that DET induces apoptosis in glioma cells by upregulating BAX and downregulating BCL2, consistent with previous studies in other malignancies." (PMID 39850823, 2024). "Studies conducted on glioma cell lines have shown that miR-16-5p binds directly to the 3′UTR of BCL-2 mRNA and deregulates cellular levels of BCL-2 mRNA and protein." (PMID 39273487, 2024). "In glioma cells, oleuropein attenuates AKT signalling, leading to the upregulation of BAX and the downregulation of BCL-2, resulting in reduced cell viability and induction of apoptosis." (PMID 39203892, 2024). "Another protein called melanoma differentiation associated gene-9/syntenin (MDA9) has been shown to maintain protective autophagy in glioma stem cells through EGFR signaling and phosphorylation of BCL2." (PMID 39062119, 2024). "Luciferase siRNA, angiopep-2 peptides, Epirubicin Let-7g miRNA, Fibrin-binding CREKA, (glioma homing peptides), Biotin Pyridoxal, p42-MAPK siRNA, KLAK, Bcl-2 and VEGF siRNA, anti-GFP siRNA, Apoptin, etc." (PMID 37006997, 2023). "miR-181d is a potential tumor suppressor in glioma that regulates important target genes involved in carcinogenesis, such as KRAS and BCL2, and is involved in lymph node metastasis in oral squamous cell carcinoma." (PMID 37372400, 2023). "MiR-181d suppresses the development of glioma cells and promotes apoptosis and cell cycle arrest via K-RAS and Bcl-2 targeting." (PMID 36882763, 2023). "Accordingly, western blotting showed that overexpression of LIMD1-AS1 resulted in higher Cyclin B1, Bcl-2, N-cadherin, and ZEB1 expression at protein levels in SF126 glioma cells." (PMID 37385987, 2023). "Treatment with let-7f decreases proliferation while increasing G1 phase cell count and apoptosis of glioma cells by decreasing CCND1, CCNE1, and Bcl-2 expression, increasing P21, P27, and Bax expression, and increasing caspase-3 activity." (PMID 37370851, 2023). "In conclusion, AKR1B1 has an antitumor effect on glioma cells by inducing the phosphorylated levels of p38 MAPK and thereby increasing the BAX/Bcl-2 ratio and caspase-3/7 activity." (PMID 37185746, 2023). "In C6 glioma cells, a parallel reduction was observed in gene expression levels of c-MYC and BCL2 after transfection with the miRNAs named vvi-miR396b, ptc-miR396f, and ptc-miR396f, compared to non-targeting controls." (PMID 37542285, 2023).